TLCD3B (TLC domain containing 3B)
Description:
Involved in ceramide synthesis.
Synonyms: FAM57B; FP1188; DKFZP434I2117; CORD22
Tractability: Antibody: UniProt predicts a signal peptide or a membrane-spanning region.
Gene: Protein-coding gene on chromosome 16 (30,024,426 to 30,052,978, reverse strand). Ensembl gene ENSG00000149926.
Subcellular location: Golgi apparatus membrane (Isoform 1); Endoplasmic reticulum membrane (Isoform 2)
Gene Ontology:
Molecular function: sphingosine N-acyltransferase activity
Biological process: ceramide biosynthetic process; lipid homeostasis
Cellular component: endoplasmic reticulum; endoplasmic reticulum membrane; Golgi membrane; membrane
Genetic constraint (gnomAD): Loss-of-function variants: 10 observed, 26.39 expected, observed/expected ratio (o/e) 0.38, 90% interval 0.23 to 0.64. The upper end of that interval is the gene's LOEUF score, 0.64, which puts it in group 2 of 6, group 1 being the genes least tolerant of losing a copy. Missense variants: 307 observed, 374.28 expected, observed/expected ratio (o/e) 0.82, 90% interval 0.75 to 0.9. Synonymous variants: 161 observed, 159.88 expected, observed/expected ratio (o/e) 1.01, 90% interval 0.88 to 1.15.
Homologues: Orthologues: chimpanzee TLCD3B (99% identical), mouse Tlcd3b (95% identical), dog TLCD3B (95% identical), macaque TLCD3B (89% identical), guinea pig TLCD3B (85% identical), rat Tlcd3b (84% identical), pig TLCD3B (77% identical), zebrafish tlcd3ba (65% identical), zebrafish tlcd3bb (64% identical), tropical clawed frog tlcd3b (62% identical), Drosophila melanogaster CG17841 (31% identical). Paralogues in human: TLCD3A (44% identical), CLN8 (20% identical), TLCD4 (16% identical), TLCD1 (14% identical), TLCD2 (13% identical).
Diseases named in the same sentence as TLCD3B in open-access papers:
TLCD3B is named in the same sentence as 54 diseases in open-access papers, as found by Europe PMC text mining. Sharing a sentence is not in itself a finding about the gene and the disease. The quoted sentences say what the papers report.
Obesity (8 papers, 2018 to 2025). Accumulation of substantial excess body fat. "DOC2A plus TLCD3B, was a top associated pair for BMI (obesity) and IQ (cognitive impairment), consistent with our data in zebrafish, CDIPT plus ALDOA the top pair for BMI, and KCTD13 plus MVP for IQ." (PMID 39988938, 2025). "Mvp loss of function increased obesity in mice in the context of a high‐fat diet and knockout of Tlcd3b was associated with increased body size in zebrafish." (PMID 39988938, 2025). "Tlcd3b may play a role in obesity as ceramides inhibit adipogenesis, through interaction with the obesity‐related gene Pparγ." (PMID 39988938, 2025).
retinal degeneration (2 papers, 2023 to 2025). Degeneration of the retina. "In a previous study, we performed gene therapy on Tlcd3b−/− mice and successfully rescued the retinal degeneration phenotypes by subretinally injecting a recombinant adeno-associated virus 8 (rAAV8) vector containing the Tlcd3b gene (rAAV8-Tlcd3b)." (PMID 37466006, 2023). "In summary, our results suggest that ceramide is a primary activator of retinal degeneration in Tlcd3b−/− mice." (PMID 37466006, 2023). "In this study, we further demonstrated that in the context of Tlcd3b-associated retinal degeneration, the disruption of overall ceramide level is not the leading cause of photoreceptor cell death." (PMID 37466006, 2023). "As previous canonical CerS-deficient mouse models failed to display retinal degeneration, the mechanisms of how TLCD3B interacts with CerSs have not been investigated." (PMID 37466006, 2023).
cone-rod dystrophy (1 paper, 2023). Inherited retinal dystrophies that belong to the group of pigmentary retinopathies. "Recently, homozygous variants in TLCD3B have been associated with cone-rod dystrophy 22, a retinal condition leading to progressive central vision loss." (PMID 38137073, 2023).
cancer (7 papers, 2012 to 2025). A tumor composed of atypical neoplastic, often pleomorphic cells that invade other tissues. "Although the other five genes RPL32, TMEM59L, LOC642929, LHX2, and TLCD3B have not been identified in clinical studies indicating their effect on cancers, they may be considered candidate oncogenes because of their high ranking in our constructed gene network modules." (PMID 33708239, 2021).
movement disorder (1 paper, 2023). Neurological conditions resulting in abnormal voluntary or involuntary movement, which may impact the speed, fluency, quality and ease of movement. "Given that many genes are found in this locus, and that there was no direct association of TLCD3B with movement disorders, we consider TLCD3B a putative DCD-associated gene." (PMID 38137073, 2023).
retinopathies (1 paper, 2023). "Future studies will explore more direct ways of ceramide delivery into the retina and test the best combination and dosage of different ceramide subtypes for treatments on Tlcd3b-associated retinopathies." (PMID 37466006, 2023). "Collectively, all these possibilities point to the delicacy of retinal ceramide subtype homeostasis in the context of Tlcd3b−/− mice, highlighting the importance to look not only at the overall ceramide level changes, but also at ceramides at the subtype level for retinopathies." (PMID 37466006, 2023).
TLCD3B also shares sentences with these, for which no sentence is quoted: tumor (5 papers); breast carcinoma (4); Insulin resistance (4); psoriasis (3); animal diseases (2); Ataxia (2); breast tumor (2); colorectal cancer (2); diabetes (2); epilepsies (2); head and neck squamous cell carcinoma (2); infection (2); neuroblastoma (2); Alzheimer disease (1); atopic dermatitis (1); autosomal recessive congenital ichthyosis (1); bladder cancer (1); cardiovascular disease (1); colitis (1); colon cancer (1); COVID-19 (1); dermatitis (1); Dystonia (1); Gaucher disease (1); Huntington disease (1); ichthyosis (1); inflammatory bowel disease (1); ischemic stroke (1); leukemia (1); liver disease (1).
A further 18 diseases each share a sentence with TLCD3B in 1 paper.